OR2T3 (olfactory receptor family 2 subfamily T member 3)
Description:
Odorant receptor.
Tractability: Small molecule: it belongs to a druggable protein family. Antibody: UniProt places it where antibodies can reach, with medium confidence; UniProt predicts a signal peptide or a membrane-spanning region; its Gene Ontology location is reachable by antibodies, with medium confidence.
Gene: Protein-coding gene on chromosome 1 (248,473,351 to 248,474,307, forward strand). Ensembl gene ENSG00000196539.
Subcellular location: Cell membrane
Pathways (Reactome):
Sensory Perception: Expression and translocation of olfactory receptors
Gene Ontology:
Molecular function: olfactory receptor activity; G protein-coupled receptor activity
Biological process: detection of chemical stimulus involved in sensory perception of smell; G protein-coupled receptor signaling pathway
Cellular component: plasma membrane; membrane
Genetic constraint (gnomAD): Loss-of-function variants: 0 observed, 0.32 expected, observed/expected ratio (o/e) 0, 90% interval 0 to 1.86. That is too few expected variants to judge how well the gene tolerates losing a copy. Missense variants: 128 observed, 221.25 expected, observed/expected ratio (o/e) 0.58, 90% interval 0.5 to 0.67. Synonymous variants: 45 observed, 89.15 expected, observed/expected ratio (o/e) 0.5, 90% interval 0.4 to 0.65.
Homologues: Paralogues in human: OR2T34 (98% identical), OR2T29 (64% identical), OR2T5 (64% identical), OR2T4 (64% identical), OR2T10 (59% identical), OR2T35 (59% identical), OR2T2 (58% identical), OR2T27 (56% identical), OR2T11 (55% identical), OR2T1 (52% identical), OR2T33 (49% identical), OR2T6 (49% identical), and 80 more.